NLRP3 (NLR family pyrin domain containing 3)
Diseases named in the same sentence as NLRP3 in open-access papers (continued):
Sharing a sentence is not in itself a finding about the gene and the disease.
COVID-19 (continued). "Here, we discuss the role of NLRP3 activation in COVID-19 and clinical trials currently underway to target NLRP3 to treat severe COVID-19." (PMID 36661317, 2023). "The lung and spleen tissue obtained from patients who died from COVID-19 exhibited higher densities of cells expressing NLRP3, IL-18, NF-κB and gasdermin D, and even HMGB-1, than age-matched controls who had died unexpectedly, but free of SARS-CoV-2-infection." (PMID 38439942, 2023). "Recently, the hyperactivation of NLRP3 inflammasome followed by IL-1β was indicated as a potential regulatory factor in the pathogenesis of COVID-19, similar to other inflammatory diseases." (PMID 37685844, 2023). "In this study, the expression of NLRP1, NLRP3, and ASC and their association with serum level of IL-1β were explored in COVID-19 patients." (PMID 37723427, 2023). "In COVID-19, an excessive immunological response results in a high level of NLRP3 inflammasome activation." (PMID 37796433, 2023). "Studies indicate that the potential activation of the NLRP3 inflammasome by SARS-CoV-2 directly leads to elevated levels of pro-inflammatory cytokines IL-1β and IL-18 in severe COVID-19 patients, which are associated with adverse outcomes." (PMID 38193087, 2023). "Here, we further highlight the therapeutic potential of inhibiting NLRP3-driven microglial activation in the COVID-19 brain using an oral drug approach with the brain-penetrant small molecule MCC950." (PMID 36316366, 2023). "Our findings suggest for the first time a possible link between COVID-19, NLRP3-mediated pyroptosis, inflammation, and APOs." (PMID 37298229, 2023). "The NLRP3 inflammasome is one of the most studied and well-explored/characterized innate immune complexes involved in COVID-19." (PMID 37243203, 2023). "Rodrigues and colleagues then provided evidence for the role of NLRP3 in COVID-19 by demonstrating its activation in PBMCs from COVID-19 patients." (PMID 36661317, 2023). "Since the beginning of the pandemic, there have been numerous attempts to develop therapeutics for COVID-19, and NLRP3 has been an attractive target." (PMID 36661317, 2023). "Correspondingly, specific inhibition of the NLRP3 inflammasome suppressed immune overactivation and alleviated COVID-19-like pathology in mice." (PMID 38439942, 2023). "CD14highCD16- monocytes derived from severe COVID-19 patients showed increased NLRP3 inflammasome activation potential, as shown by the formation of ASC speck/caspase-1 complexes and increased IL-1β secretion." (PMID 37251383, 2023). "Since caspase-1-independent pathway also gives rise to enhanced IL-18 secretion, the relationship between NLRP3 inflammasome activation and COVID-19 development is an important subject to be further addressed." (PMID 37251383, 2023). "Reportedly, NLRP3 inflammasome was activated in peripheral blood mononuclear cells (PBMCs) from COVID-19 patients." (PMID 37251383, 2023). "Much evidence showed that there are many similar inflammatory pathways between periodontitis and COVID-19, such as NF-κB pathway, NLRP3/IL-1β pathway, and IL-6 signaling pathway." (PMID 36769328, 2023). "Activation of NLRP3 inflammasome plays an important role in maintaining endothelial cell function in COVID-19." (PMID 37868953, 2023). "In this review, we summarise recent findings on NLRP3 in COVID-19 during the acute phase of the disease and the therapeutic targeting of NLRP3." (PMID 36661317, 2023). "Activation of NLRP3-inflammasomes is more common in Strongyloides infection; therefore, this type of helminths aggravate COVID-19 pathology and hyperinflammation." (PMID 37383608, 2023). "A recent study indicated that NLRP3 inflammasome was hyperactivated in neutrophils from severe COVID-19 patients." (PMID 37251383, 2023). "Collectively, caspase-4 acted as a master factor mediating NLRP3 inflammasome activation and COVID-19 pathology." (PMID 37251383, 2023).
COVID-19 (continued). "On one hand, the present results appear to contradict previous studies that have demonstrated an increase in NLRP3 parameters in both COVID-19 and septic patients." (PMID 38140660, 2023). "Consistent with previous studies, activated NLRP3 inflammasome, accompanied by IL-1β release, was observed in circulating monocytes from severe COVID-19 patients." (PMID 37251383, 2023). "Severe COVID-19 neutrophils exhibited impaired responsiveness to NLRP3 insults (e.g., ATP and bacterial LPS)." (PMID 37251383, 2023). "Microglia exposed to SARS-CoV-2, or its spike protein, also potentiated α-synuclein mediated NLRP3 activation, indicating a possible mechanism for COVID-19 and increased vulnerability to developing movement disorders in certain infected individuals." (PMID 36316366, 2023). "Opposed potentials of caspase-1 activation were observed between nonclassical monocytes and immature neutrophils from severe/critical COVID-19 patients upon NLRP3 inflammasome stimulation." (PMID 37251383, 2023). "The activation of NLRP3 during COVID-19 infection is via ACE-2 which is highly expressed at the monocyte of COVID-19 patients only." (PMID 37360532, 2023). "This conclusion is further supported by the observation that lung alveolar epithelial cells obtained from autopsy samples of COVID-19 patients who passed away exhibit significant activity of the NLRP3 inflammasomes." (PMID 38259635, 2023). "Results from a pilot study demonstrate that blocking NLRP3 inflammasome signaling exhibits potency in reducing COVID-19 immunopathology." (PMID 37515138, 2023). "Among all the inflammasomes, the nucleotide-binding oligomerization domain-like receptor containing pyrin domain 3 (NLRP3) inflammasome is the best studied and one of the most involved in COVID-19." (PMID 36829456, 2023). "NLRP3 inflammasome activation of nonclassical monocytes was elevated with increasing COVID-19 severity, while CD66b+CD16dim granulocytes exhibited lower NLRP3 activation potential in severe forms of COVID-19 than mild cases." (PMID 37251383, 2023). "This study aimed to evaluate the expression of NLR family pyrin domain containing 1 (NLRP1), NLRP3, and Apoptosis-associated speck-like protein containing a CARD (ASC) as well as their association with serum level of interleukin (IL)-1β in patients with coronavirus disease 2019 (COVID-19)." (PMID 37723427, 2023). "The mechanism responsible for COVID-19 exosome-induced NLRP3 inflammasome activation is worthy of more detailed investigation." (PMID 37251383, 2023). "The analysis of samples from moderate and severe COVID-19 cases indicated active NLRP3 inflammasome in PBMCs and tissues of postmortem patients." (PMID 36899820, 2023). "They suggest that fatal COVID-19 involved excessive activation of cytotoxic cells and the NLRP3 (nucleotide-binding domain, leucine-rich-containing family, pyrin domain-containing-3) inflammasome." (PMID 37465683, 2023). "The colocalization of SARS-CoV-2, ACE2, and NLRP3 within neurons, astrocytes, and microglia was also found in cerebral cortical tissue in three post-mortem COVID-19 cases." (PMID 36316366, 2023). "NLRP3 activation has been positively correlated with COVID-19 disease severity and prognosis in the acute phase." (PMID 36661317, 2023). "The NLR family pyrin domain containing 3 (NLRP3) inflammasome plays a central role in the cytokine storm observed during both COVID-19 and periodontal inflammation." (PMID 37893162, 2023). "In this review, we summarize current evidence supporting the pathogenetic role of the NLRP3 inflammasome and IL-1β in COVID-19, and discuss clinical trials testing IL-1 inhibition in COVID-19." (PMID 36209522, 2022). "On the other hand, a decreased level of H2S has been reported in the plasma of patients with COVID-19, which suggests increased activity of NLRP3 and an aggravation of inflammation." (PMID 35739949, 2022).
COVID-19 (continued). "STRING database was used to analysis core intersection targets of LHQW and COVID-19, 13 core protein targets (including: NLRP3, TNF, CSF2, IFNG) were obtained by setting confidence degree (confidence degree>0.95)." (PMID 36506032, 2022). "In summary, COVID-19 has resulted in a range of disease manifestations, the most severe of which is mediated by a massive inflammatory response that stimulates the NLRP3 inflammasome." (PMID 36248872, 2022). "As the NLRP3 inflammasome plays important roles in the pathogenesis of COVID-19 and cardiovascular disease, colchicine was tested for its potential inhibitory activity towards the NLRP3 inflammasome." (PMID 35669789, 2022). "This latest technology presents the benefit of studying the caspase 1 activation in specific cell types and subpopulations and has been used to investigate the NLRP3 inflammasome activation in COVID-19 patients." (PMID 36291172, 2022). "A phase 2, randomized, double-blind, placebo-controlled study evaluating dapansutrile (an orally administered NLRP3 inhibitor) in patients with moderate COVID-19 is currently ongoing (NCT04540120)." (PMID 36209522, 2022). "The tissues of postmortem COVID-19 patients show the active NLRP3 inflammasome and its products, including IL-1β, IL-18, and LDH." (PMID 35639261, 2022). "Tranilast, an old anti-allergy clinical drug is a direct NLRP3 inhibitor that has entered clinical trials for the treatment of COVID-19 patients." (PMID 35784277, 2022). "Since the outbreak of COVID-19 in December 2019, which was caused SARS-CoV-2, COVID-19-associated ALI/ARDS has been widely discussed, and the role of NLRP3 inflammasome in its progressing has received great attention." (PMID 36618363, 2022). "Lastly, the NLR family pyrin domain containing 3 (NLRP3) is the most acknowledged inflammasome pattern which takes place in COVID-19, including most of the immune-inflammatory pathways elucidated above." (PMID 35270015, 2022). "Compared to the available knowledge, our current study was focused on mostly in vivo study to uncover the importance of NLRP3 inflammasome in COVID-19 lung immunopathology." (PMID 34979342, 2022). "The use of the small molecule MCC950, a specific inhibitor of NLRP3 inflammasome activity, alleviated COVID-19 like pathology in hACE2 transgenic mice." (PMID 35807916, 2022). "In this review, we summarize current evidence supporting the involvement of the NLRP3 inflammasome and IL-1β in the pathogenesis of COVID-19." (PMID 36209522, 2022). "The NLRP3 inflammasome is activated upon SARS-CoV-2 infection and associated with COVID-19 severity." (PMID 34979342, 2022). "Nevertheless, despite these caveats this study identifies vascular endothelial NLRP3 inflammation, and documents thrombi and altered vascular structures in the lungs of fatal COVID-19 patients." (PMID 35144622, 2022). "COVID-19 alters innate immune responses by viroporin-mediated NLRP3-inflammasome activation, increasing IL-1β expression." (PMID 36034552, 2022). "Molecular docking showed that I-SPD, Pachypodol and Vestitol in XFBD played a role in treating COVID-19 by acting on NLRP3, CSF2, and relieve the clinical symptoms of SARS-CoV-2 infection." (PMID 36034710, 2022). "The contribution of the NLRP3-inflammasome in neutrophils during viral infection has recently emerged during COVID-19." (PMID 35406754, 2022). "The outcomes of this study will provide scientific-based evidence to support the use of C. petasites extract and its bioactive flavonoids as therapeutic strategies for COVID-19-related chronic inflammation by targeting the NLRP3 inflammasome pathway." (PMID 36142258, 2022). "4-HNE is a well-known modulator of cellular functions and was found to induce NLRP3, resulting in inflammasome activation, while it is also acknowledged as a reliable biomarker of ferroptosis, occurring also in lethal COVID-19." (PMID 35159254, 2022).
COVID-19 (continued). "In conclusion, our current study demonstrated that targeting NLRP3 inflammasome by MCC950 is a potential treatment for COVID-19 related immunopathology in mouse models." (PMID 34979342, 2022). "During COVID-19, the NLRP3 inflammasome is overactivated, leading to the production of IL-1β/18 and promoting cytokine storm." (PMID 36034710, 2022). "According to the increased inflammasome activation, we observed that NLRP3 mRNA expression was significantly overexpressed in the tracheal tissue of COVID-19 patients who died due to COVID-19 and in patients who died within 28 days of hospital admission." (PMID 36498845, 2022). "Simultaneously, with complement factors known to be activated in COVID-19 and also a priming agent for NLRP3 signaling, the diseased state can be thought as an interplay between IL-1 and complement system." (PMID 35431536, 2022). "A potential activator of NLRP3 is reactive oxygen species (ROS), so it is thought that their excessive production resulting from inflammation in COVID-19 leads to NLRP3 activation and cleavage of the IL-1β precursor which potentiates inflammation." (PMID 35562935, 2022). "Many papers have addressed the association of elevated plasma IL-18 level with mortality in ARDS, emphasizing the connection between NLRP3 inflammasome and COVID-19 progression." (PMID 36052163, 2022). "The observation of NLRP3 inflammasome activation in vivo in COVID-19 patients and subsequent studies treating severe patients with experimental anti-pro-inflammatory cytokines allowed for the underlying molecular mechanisms to also be studied." (PMID 35626754, 2022). "The NLRP3 inflammasome pathway in myeloid cells partially accounts for the cytokine storm in COVID-19 patients." (PMID 36263178, 2022). "This review has shed light on the close relationship between mitochondrial dysfunction, NOX, ROS, NLRP3 inflammasome, TLRs, and NO as the “inflammatory circuit” of COVID-19." (PMID 35639261, 2022). "Inhibition of the NLRP3 inflammasome attenuated the release of COVID-19 related pro-inflammatory cytokines in cell cultures and mice." (PMID 34979342, 2022). "NLRP3 inflammasome activation in the blood of patients reveals an impaired immature neutrophil response in severe COVID-19." (PMID 35720378, 2022). "The use of small molecule MCC950, a specific inhibitor of NLRP3 inflammasome activity, alleviated COVID-19 like pathology in human ACE2 (hACE2) transgenic mice." (PMID 34979342, 2022). "As evidence was mounting, a pathogenetic role for the NLRP3 inflammasome/IL-1β signalling pathway in COVID-19 was established." (PMID 36209522, 2022). "NLRP3-stimulation has been shown to intensely induce cytokine expression during the cytokine storm in COVID-19 and periodontitis." (PMID 35047633, 2022). "For example, SARS-CoV-2 infected blood monocytes to activate the NLRP3 inflammasome, and lead to the formation of a COVID-19 related cytokine storm." (PMID 34979342, 2022). "Pachypodol, I-SPD and Vestitol in XFBD play a role in treating COVID-19 by acting on NLRP3, CSF2, and relieve the clinical symptoms of SAR-Cov-2 infection." (PMID 36034710, 2022). "Suppression of NLRP3 inflammasome by genetic knockout and specific inhibitor in the mouse models consistently displays its immune importance in COVID-19 disease progression." (PMID 34979342, 2022). "Activation of the NLRP3 inflammasome is also seen in peripheral blood mononuclear cells (PBMCs) and tissues of postmortem patients with COVID-19 upon autopsy." (PMID 36419185, 2022). "As a novel finding, NLRP3 was related to TF concentration in COVID-19 patients, suggesting a plausible link between eATP dysregulation and TF release." (PMID 35173744, 2022). "Flow cytometry analysis confirmed increased intracellular IL-18 and NLRP3 inflammasome expression in CD14+ monocytes of the patient with COVID-19 vaccine-related myopericarditis." (PMID 35251049, 2022).
COVID-19 (continued). "An active NLRP3 inflammasome in peripheral blood mononuclear cells (PBMCs) and tissues of postmortem patients upon autopsy from COVID-19 patients was also reported, although a supporting mechanism for the observation was not well defined." (PMID 35587188, 2022). "The NLRP3 inflammasome, consisting of NLRP3, ASC, and caspase-1, is activated in response to SARS-CoV-2 infection and is active in COVID-19 patients, which is associated with the clinical outcome of the disease." (PMID 35655782, 2022). "Collectively, these in vivo data demonstrated that Nlrp3 deficiency disables SARS-CoV-2 induced inflammasome activation and thus inhibits inflammatory responses to alleviate COVID-19 like immunopathology in lungs." (PMID 34979342, 2022). "Both the P2X7 receptor and NLRP3 have been considered as potential pharmacological targets for treating inflammation in COVID-19." (PMID 35663992, 2022). "In summary, we showed novel evidence on the activation of inflammasome in critically ill COVID-19 patients, as well as the correlation with NLRP3 activation and severity." (PMID 36498845, 2022). "Lungs from COVID-19 ARDS subjects co-labeled for NLRP3 and caspase 1, showed colocalization (yellow) along the vessel wall." (PMID 35144622, 2022). "In this regard, SARS-CoV-2 in vitro infection can induce NLRP3 activation in human peripheral blood monocytes, and NLRP3 is activated in blood monocytes from COVID-19 patients." (PMID 36498845, 2022). "NLRP3 activation has been proposed as an indicator of COVID-19 disease severity, predicting the release of pro-inflammatory cytokines that lead to dysregulated immune responses and tissue damage." (PMID 35244141, 2022). "In the lung tissues of Nlrp3-KO mice, the mRNA levels of these COVID-19 related chemokines were reduced relative to C57BL/6J mice upon SARS-CoV-2 infection." (PMID 34979342, 2022). "A phase II clinical trial of selective NLRP3 inflammasome inhibitor Dapansutrile for moderate COVID-19 with early cytokine release syndrome is recruiting (NCT04540120)." (PMID 35697684, 2022). "In peripheral blood immune cells and tissues of COVID-19 patients, activated NLRP3 inflammasome, caspase-1, and high levels of GSDMD-NT were found, as well as elevated expression of IL-1β and IL-18 in serum." (PMID 36532040, 2022). "The appraisal of clinical efficacy of several compounds with modulatory effects on NLRP3 inflammasome activity in COVID-19 treatment is currently being addressed." (PMID 36263178, 2022). "Therapeutic targeting of the particular inflammasome (NLRP3) pathway is currently in various stages of research and is expected to show beneficial effects in patients with severe COVID-19." (PMID 36132227, 2022). "COVID-19 provokes an NLRP3-mediated increase in IL-1β expression, similar to the NLRP3-inflammasomopathies." (PMID 36034552, 2022). "We observed a significant induction of NLRP3, caspase-1, and interleukin-1β (IL-1β) mRNA expression in endothelial cells following exposure to exosomes from severe COVID-19 patients compared with that from patients with mild disease or healthy donors." (PMID 35587188, 2022). "Researchers have demonstrated that metformin treatment prevents and ameliorates ARDS induced by LPS in mice, accompanied by abrogated NLRP3 inflammasome activation in macrophages, and attenuates pulmonary inflammation in COVID-19 patients." (PMID 35910360, 2022). "MCC950 treatment also alleviates excessive lung inflammation and COVID-19–like pathology in adeno-associated virus (AAV)-hACE2 transgenic mice, indicating that the NLRP3 inflammasome induces excessive inflammatory responses during SARS-CoV-2 infection." (PMID 36419185, 2022). "Both alterations in functions of neutrophils and the NLRP3 inflammasome appear to contribute to COVID-19 pathogenesis." (PMID 35406754, 2022). "For COVID-19 affected subjects, fluorescence around the vessel walls implied NLRP3 expression along the endothelial layer (two upper panels)." (PMID 35144622, 2022).